BDNF (brain derived neurotrophic factor)
Diseases named in the same sentence as BDNF in open-access papers (continued):
Sharing a sentence is not in itself a finding about the gene and the disease.
depression (continued). "The results are consistent with several previous studies, strongly indicating the disruption of BDNF signaling in depression and the restoration processes induced by antidepressant treatment." (PMID 28375203, 2017). "Evidence demonstrates that brain-derived neurotrophic factor (BDNF) has a pivotal role in the pathogenesis of major depressive disorder (MDD)." (PMID 28375203, 2017). "Brain-derived neurotrophic factor (BDNF) has often been suggested to contribute to the pathophysiology of major depressive disorder (MDD)." (PMID 29387021, 2017). "Peripheral reductions in mature BDNF in serum and plasma have been noted in persons with depression and in cases of suicide, and psychosocial stress appears to exert a role in these decrements." (PMID 28928987, 2017). "Elevating hippocampal BDNF levels attenuates chronic stress in a mouse model of depression, while chronic administration of antidepressant drugs increases BDNF expression within the hippocampus." (PMID 28872625, 2017). "Human studies reveal that individuals with depression have significantly lower circulating BDNF compared to healthy controls." (PMID 29056915, 2017). "The significances of the lower BDNF levels in the peripheral blood from subjects with depression were recently reported worldwide in many clinical studies." (PMID 28241064, 2017). "Moreover, abundant evidences provide the basis for the neurotrophic hypothesis of depression which associates decreased BDNF expression with depression and increased BDNF expression with antidepressant action, effects possibly mediated by alterations in neurogenesis." (PMID 28373887, 2017). "Simultaneously, it has been shown that the therapeutic effects of antidepressants require the action of the BDNF/TrkB pathway and, furthermore, that centrally administered BDNF provides a similar effect to antidepressants in animal models of depression." (PMID 28134845, 2017). "Numerous studies have reported decreased BDNF levels in patients with bipolar depression and mania, along with low levels of BDNF to be correlated with severity of depression and mania symptoms." (PMID 29232923, 2017). "Consumption of probiotics was also shown to increase expression of brain-derived neurotrophic factor (BDNF), a growth factor crucial for brain plasticity, memory, and neuronal health that is abnormally reduced in patients suffering from depression." (PMID 28239408, 2017). "Recent findings showed that cAMP response element-binding protein (CREB)—brain derived neurotrophic factor (BDNF) pathway in the HPC was closely related in depression and antidepressants." (PMID 29163055, 2017). "Treatment with antidepressant drugs significantly elevates circulating BDNF and these changes are significantly correlated with improved depression scores." (PMID 29056915, 2017). "There is a well-established body of clinical evidence implicating the involvement of BDNF in the pathobiology of depression." (PMID 28928987, 2017). "The role of BDNF in the pathophysiology of depression is further supported by the observation that the long-term administration of antidepressants in animals upregulates the production of brain BDNF." (PMID 29348904, 2017). "Considering these important roles of BDNF in depression, we examined hippocampal BDNF levels in our model." (PMID 29138442, 2017). "Immunofluorescence assay showed that BDNF (red fluorescence) in depression mice was significantly lower compared with control mice." (PMID 28761074, 2017).
depression (continued). "Reduced BDNF levels are a consistent finding in animal models of depression, and administration of exogenous BDNF into the hippocampus is able to produce antidepressant behavioral responses comparable to antidepressant medications." (PMID 28828187, 2017). "In case of a study done on humans for assessing the levels of BDNF in depression patients on antidepressants only those patients who had received antidepressants for 3 weeks or more, were recruited in the study quite like the animal studies." (PMID 29209221, 2017). "It is known that both BDNF and 5-HT signaling systems regulate the development and plasticity of neural circuits involved in important mood disorders like depression and anxiety." (PMID 28487628, 2017). "Independent t-tests were performed to assess differences between scores of depression, self-efficacy, and loneliness as a function of BDNF genotype." (PMID 28769852, 2017). "The neurotrophic hypothesis of depression proposes that stress-related alterations in BDNF levels occur in key limbic structures to contribute to the pathogenic processes in MDD." (PMID 28928987, 2017). "It was observed that chronic consumption of SFA induced depression-like behavior in the forced-swim test, accompanied by increased striatal levels of BDNF." (PMID 28304335, 2017). "In a murine model of depression it was demonstrated that chronic peripheral infusion of BDNF resulted in antidepressant behavioral and neuronal adaptations." (PMID 29056915, 2017). "Chronic stress reduces brain-derived neurotrophic factor (BDNF) in the hippocampus and prefrontal cortex and increases neuroinflammation, an alteration noted in the formation of depression." (PMID 28607630, 2017). "In human postmortem brains collected from suicide victims with major depression, a decrease in TrkB messenger RNA (mRNA) and BDNF mRNA levels was found in the prefrontal cortex and hippocampus." (PMID 27975125, 2017). "Depression-like symptoms (the signs of behavioral despair or anhedonia), deficits in working memory and sensorimotor gating also co-occurred with decreased BDNF expression." (PMID 28620285, 2017). "After treatment with SCE, the BDNF levels were upregulated, and the depression symptoms and cognition decline were alleviated at the same time according to the behavioral results." (PMID 28761074, 2017). "Independent t-tests were performed to assess differences between scores of depression, problem-focused and emotion-focused coping, and loneliness as a function of BDNF genotype." (PMID 28769852, 2017). "In animal models of depressive disorder, change in expression levels of BDNF and the rate of neurogenesis has been extensively studied." (PMID 29099059, 2017). "Acute and chronic stress purportedly have detrimental effects on rodent BDNF expression in the hippocampus, while altered BDNF levels are evident in depressive disorders and in schizophrenia." (PMID 28855875, 2017). "Growing evidence indicates that selective serotonin reuptake inhibitors (SSRIs that are used in the treatment of depressive disorders) increase the expression of BDNF." (PMID 29099059, 2017). "Animal studies show that the use of agomelatine, an antidepressant drug, for the treatment of depressive disorders leads to an increase in BDNF expression in the prefrontal cortex and in the hippocampus." (PMID 29299044, 2017). "Non-drug treatments for depression, such as Electroconvulsive Therapy (ECT), also generate an increase in BDNF expression in the brain, which further underscores the linkage of BDNF levels with depressive disorders." (PMID 29299044, 2017). "Neurogenesis in the hippocampus was previously reported to be suppressed during depression, and chronic treatments with SSRIs increased the expression of BDNF, proliferation/differentiation of neuronal progenitor cells, and maturation of newborn neurons." (PMID 27120588, 2016).
depression (continued). "The identification of these molecules is of great interest as many people afflicted with depression or with neurodegenerative diseases are likely to benefit from the ability of exercise to stimulate BDNF through small metabolites, such as DBHB." (PMID 27253067, 2016). "Rodent models of depression show reduced expression levels of BDNF and its receptor Tropomyosin receptor kinase B (TrkB)." (PMID 26869919, 2016). "In addition, since the serum TPOAb measured in the T group was significantly higher than in the C group not only before pregnancy but also post-partum, we cannot determine whether the higher TPOAb titer could increase the risk of depression and reduce the levels of BDNF and 5-HT before pregnancy." (PMID 28119573, 2016). "It is probable that social defeat stress causes decreased BDNF in the hippocampus and PFC, but increased BDNF in the NAc, resulting in depression-like behavior in mice." (PMID 27488193, 2016). "It has been reported, however, that in particular mature BDNF is important in major depression although this needs exploration." (PMID 27092550, 2016). "Kleimann and colleagues, for the first time, examined an effect of electroconvulsive therapy (ECT) on DNA methylation of BDNF in treatment-resistant major depressive patients." (PMID 27267954, 2016). "Our results revealed limited EET effects in decreasing depression-like behavior or inducing BDNF levels in either the hippocampus or frontal cortex in old adult KIV mice." (PMID 27648918, 2016). "The BDNF protein has been extensively studied as an important factor involved in the pathogenesis of a wide range of psychiatric disorders, such as major depression, schizophrenia and bipolar disorders." (PMID 27267954, 2016). "In conclusion, the results showed that exposure to CS during prenatal (maternal exposure) and early postnatal life increased the depression-like behaviors and decreased BDNF/TrkB signaling later in life." (PMID 26503133, 2016). "The aim of the present study was to investigate the regulation of acupuncture on the depressive-like behaviors and the ERK signaling pathway as well as BDNF protein expression in chronic unpredictable mild stress (CUMS)-induced depression model rats." (PMID 27680977, 2016). "The rTMS treatment is reported to result in significant increases in serum levels of total BDNF (mature BDNF + proBDNF) in patients with depression." (PMID 27007747, 2016). "Patients with mild depression had a significantly higher level of serum BDNF (45.283 ± 4.213 pg/ml) than those with moderate (33.178 ± 4.289 pg/ml, P < 0.001) or severe depression (28.190 ± 3.143 pg/ml, P < 0.001)." (PMID 27852063, 2016). "In addition, the brain-derived neurotrophic factor (BDNF) hypothesis implies that an increase in BDNF at the VT area and nucleus accumbens (NAc) may increase neurovegetative symptoms associated with depression." (PMID 27524960, 2016). "This means that depression significantly reduced the level of serum BDNF and that it indirectly affected the prognosis of the patients via BDNF regulation." (PMID 27852063, 2016). "Physical exercise enhances circulating BDNF, down-regulates systemic inflammation and is recognized as an effective treatment for depression and anxiety." (PMID 27832209, 2016). "In the present study, we have assessed serum and plasma BDNF levels, preschool child IQ, inattention, hyperactivity, internalized/externalized problems, behavioral problems and depression in preschool children (age range 5–7 years)." (PMID 27200107, 2016). "In conclusion, these findings suggest that increased BDNF–TrkB signaling in the NAc plays a key role in depression phenotype of α7 nAChR KO mice." (PMID 27821848, 2016). "Hit one represents polymorphisms in the AR, BDNF, 5HTTLPR, FKBP5, and NR3C1, which independently increase the risk of developing depression, AUDs, and suicidal behavior in men." (PMID 28096796, 2016).
depression (continued). "We found that patients with severe depression displayed a downregulated level of serum BDNF and that the level of serum BDNF was highly correlated with the OS of the patients (R2 = 0.2292)." (PMID 27852063, 2016). "Low serum BDNF protein levels have been found in patients with depression, schizophrenia, anxiety and borderline personality disorder." (PMID 27267954, 2016). "For example, chronic duloxetine administration increases PFC BDNF mRNA and protein levels in animal models for depression, correlating with an improvement in emotional behaviors." (PMID 27757074, 2016). "Previously, it was reported that intra-VTA BDNF injections lead to depression-like behavior, while a blockade of BDNF activity in the NAc produced antidepressant-like effects." (PMID 27488193, 2016). "BDNF is considered an effector of the transcription of immediate-early genes, which are expressed in response to depression." (PMID 27852063, 2016). "While certain treatments with antidepressants increased levels of BDNF in serum, a pre-treated level of BDNF has been shown to possibly predict the response to antidepressant treatment and has been correlated with depression rating improvements during therapy." (PMID 27267954, 2016). "Compromised function of plasticity and BDNF signaling has been implied in the pathophysiology of depression." (PMID 26503133, 2016). "The Self-Rating Depression Scale score showed an inverse correlation with serum BDNF levels, while demonstrating a direct correlation with miR-132 levels." (PMID 27527165, 2016). "Further studies are needed to identify the effects of antidepressants on blood levels of mature BDNF and proBDNF using larger sample sizes, to clarify their physiological mechanisms in mood disorders such as major depression and bipolar disorder." (PMID 27777607, 2016). "BDNF is reportedly involved in the pathophysiology of both PD and depression, as evidenced by the fact that altered expression of BDNF mRNA and protein has been observed in postmortem studies of PD patients." (PMID 27525025, 2016). "It is reported that rTMS increases blood BDNF (mature BDNF + proBDNF) levels in patients with depression." (PMID 27007747, 2016). "This study aimed to test for association between antidepressant-worsening suicidal ideation and polymorphisms of BDNF/NTRK2 neurotrophin pathway genes, known to be involved in depression and suicide." (PMID 27378793, 2016). "Its involvement in psychiatric conditions is well described and was confirmed by a meta-analysis, as in major depressive disorder, the decreased serum BDNF (seBDNF) level was elevated following a course of antidepressant treatment." (PMID 27478486, 2016). "Recently, studies have suggested that brain derived neurotrophic factor (BDNF) plays an important role in the development of depression." (PMID 27852063, 2016). "A study using postmortem brain samples showed increased BDNF levels in the NAc of depression patients, implying a key role for increased BDNF–TrkB signaling in NAc for the development of depression." (PMID 27821848, 2016). "Further, enhanced BDNF expression has been found in the nucleus accumbens of individuals with depression." (PMID 27525025, 2016). "Sex steroids were shown to increase BDNF protein levels in human neurons suggesting sex steroids to have additional protective effects against depression due to the promotion of neuroplasticity." (PMID 28096796, 2016). "There was also a sex difference in basal VEGF, and while most of the focus on stress, depression, and neuroplasticity has been directed toward BDNF, VEGF is also a potent mediator of neuroplasticity." (PMID 34055816, 2016). "The physiological mechanisms and dynamics of serum mature BDNF and proBDNF levels in mood disorders such as major depression and bipolar disorder are still unclear and remain to be elucidated." (PMID 27777607, 2016).
depression (continued). "In the recent study of Chagnon and colleagues, a significantly higher methylation level of one BDNF region (exon VI, 3 CpG sites) was observed in older women with anxiety and/or depression compared with controls." (PMID 27267954, 2016). "Activity-dependent BDNF secretion has been reported to be required for long-term potentiation and depression while impaired patterns of discrimination and learning deficits have been observed in BDNF knockout mice." (PMID 27494844, 2016). "A clinical study in 2004 showed that serum BDNF levels were negatively correlated with depression-related personality traits." (PMID 27852063, 2016). "BDNF is considered as a critical marker and mediator of mood disorders, particularly major depression and assumed to be involved in the etiology, pathogenesis, and treatment response to antidepressants." (PMID 28074100, 2016). "The purpose of our present work is to look for a rapid-onset and long-lasting therapeutic strategy for major depressive disorder (MDD) by effectively delivering BDNF to brain." (PMID 26935651, 2016). "Meanwhile, reduced expression of BDNF mRNA and protein has been found in the mesostriatal and mesocorticolimbic pathways, as well as in the serum of patients with depression." (PMID 27525025, 2016). "It was reported that intra-VTA BDNF injections lead to depression-like behavior, while a blockade of BDNF activity in the NAc produced antidepressant effects." (PMID 27821848, 2016). "In the subsequent study, these authors extended the BDNF promoter I methylation level analysis to the group of patients with major depression on stable pharmacologic treatment in comparison with healthy individuals." (PMID 27267954, 2016). "We recommend prospective analyses to underpin downregulation of the cortisol:BDNF pathway, as well as the use of a validated depression score to substantiate chronic emotional distress and its relationship with cortisol:BDNF ratio." (PMID 27966001, 2016). "An early study proved that a reduction in BDNF in the hippocampus affects several behaviors related to depression." (PMID 27680977, 2016). "Afterwards, serum and plasma BDNF levels were found to be decreased in patients with depressive disorder." (PMID 27852063, 2016). "Levels of BDNF in patients with depressive disorders and levels of ipsilesional GABA in stroke survivors are biomarkers commonly cited in the literature." (PMID 27486393, 2016). "In sum, throughout the literature one encounters an inconsistent picture for the relationship between BDNF and depressive disorders, AUDs, and suicidal behavior." (PMID 28096796, 2016). "Mean age did not seem to contribute to heterogeneity in between-group meta-analyses comparing peripheral BDNF levels of participants in depression or euthymia compared to their respective healthy controls." (PMID 26621529, 2015). "We were the first to discover that rhythmic moderate exercise promoted T cell regulatory function, improved depression symptoms, and increased levels of BDNF." (PMID 26075212, 2015). "Alcohol intake and body mass index, as well as depression, serum BDNF and serum VEGF were identified as predictors of serum sortilin levels in our final multivariate model." (PMID 26556286, 2015). "BDNF has been extensively studied in patients with major depression, and has been demonstrated that patients with the acute disorder have lower serum BDNF than when euthymic and than controls." (PMID 25947167, 2015). "BDNF/TrkB levels are also posited to be involved with depression pathology and are diminished in post mortem studies (albeit based on suicide cases and having not been replicated by independent research groups)." (PMID 25806005, 2015). "For example, in a small study involving 41 patients with major depression, low serum BDNF levels predicted treatment failure and higher depressive symptomology." (PMID 25886523, 2015).